RN7SL217P (RNA, 7SL, cytoplasmic 217, pseudogene)
Gene: Miscellaneous RNA gene on chromosome 3 (49,863,375 to 49,863,660, reverse strand). Ensembl gene ENSG00000264706.
Homologues: Orthologues: chimpanzee Metazoa_SRP (100% identical), macaque Metazoa_SRP (90% identical). Paralogues in human: RN7SL3 (84% identical), RN7SL1 (83% identical), RN7SL2 (83% identical), RN7SL220P (81% identical), RN7SL478P (80% identical), RN7SL357P (79% identical), RN7SL448P (79% identical), RN7SL218P (79% identical), RN7SL296P (79% identical), RN7SL408P (79% identical), RN7SL556P (79% identical), RN7SL575P (79% identical), and 703 more.